C10orf55 (chromosome 10 putative open reading frame 55)
Synonyms: bA417O11.3
Gene: Long non-coding RNA gene on chromosome 10 (73,908,103 to 73,922,810, reverse strand). Ensembl gene ENSG00000222047.
Diseases named in the same sentence as C10orf55 in open-access papers:
C10orf55 is named in the same sentence as 13 diseases in open-access papers, as found by Europe PMC text mining. Sharing a sentence is not in itself a finding about the gene and the disease. The quoted sentences say what the papers report.
head and neck squamous cell carcinoma (2 papers, 2022 to 2024). A squamous cell carcinoma that arises from any of the following anatomic sites: lip and oral cavity, nasal cavity, paranasal sinuses, pharynx, larynx, and salivary glands. "C10orf55 is among the four most significant genes correlated with plasminogen activator urokinase, a factor that is related to poor clinical results in head and neck squamous cell carcinoma." (PMID 38960987, 2024).
acute myeloid leukemia (1 paper, 2022). Acute myeloid leukemia (AML) is a group of neoplasms arising from precursor cells committed to the myeloid cell-line differentiation. "Although AC083799.1, C10orf55, and GNas.AS1 have not been reported in glioma, some studies have found that they play important roles in the occurrence and development of other tumors, such as breast cancer, colon cancer, acute myeloid leukemia, and endometrial cancer." (PMID 36033510, 2022).
bleeding disorder (1 paper, 2017). "As other hematopoietic lineages, and the other duplicated gene, C10orf55, had not been studied in QPD, we further explored the nature of the PLAU regulatory defect in this bleeding disorder." (PMID 28301587, 2017).
esophageal adenocarcinoma (1 paper, 2022). A malignant tumor with glandular differentiation arising predominantly from Barrett mucosa in the lower third of the esophagus. "Another cancer in which C10orf55 plays an important role is esophageal adenocarcinoma." (PMID 36294833, 2022).
tumor (3 papers, 2021 to 2022). "The in vivo and in vitro results suggest an involvement of C10orf55 in tumor cell proliferation and migration." (PMID 36294833, 2022). "Besides, we found that AC138035.1, C10orf55, AP005899.1, AC008734.1, AL021154.1 and AC130462.2 were upregulated in tumour tissues than those in adjacent normal tissues, whereas MIR3945HG was downregulated." (PMID 35778526, 2022).
cancer (2 papers, 2022 to 2023). A tumor composed of atypical neoplastic, often pleomorphic cells that invade other tissues. "Thus, C9orf50, C9orf64, C5orf66, C16orf74 and C10orf55 genes are most mentioned in the cancer context (each gene was mentioned at least in six publications), while 42 out of 92 genes are mentioned in one publication only." (PMID 37373333, 2023).
C10orf55 also shares sentences with these, for which no sentence is quoted: head and neck cancer (2 papers); breast carcinoma (1); colon cancer (1); endometrial cancer (1); glioma (1); osteosarcoma (1); platelet disorder (1).